INS (insulin)
Diseases named in the same sentence as INS in open-access papers (continued):
Sharing a sentence is not in itself a finding about the gene and the disease.
preeclampsia (continued). "In contrast to glyburide and insulin, metformin decreases maternal insulin levels, which could be the reason for the observed improvements regarding maternal adaptation to pregnancy such as reduction of preeclampsia risk also highlighted in metformin intervention studies in obese mice in our lab." (PMID 35258482, 2022). "In addition, there is small but consistent evidence showing that the daily consumption of probiotics may reduce the risk of preeclampsia, maintain serum insulin levels and reduce the frequency of GDM in pregnant women." (PMID 27724923, 2016). "The altered gene products in adipose tissue lead to suppression of preeclampsia-associated inflammation which in turn is responsible for excessive production of Th2 type cytokines and host defense molecules, as well as modulation of adipogenesis and insulin resistance." (PMID 26089598, 2015). "Among these genes, the greatest up- or downregulation was observed in genes involved in immune response, oxidative stress, and insulin and lipid metabolism, any of which may contribute to the molecular mechanisms underlying insulin resistance and adipogenesis in preeclampsia." (PMID 26089598, 2015). "The associations, except for insulin, remained significant in sensitivity analyses excluding pregnancies complicated by GDM and preeclampsia." (PMID 39915864, 2025). "Exercise improves cardiovascular function, reduces inflammation, enhances insulin sensitivity, and promotes healthy weight gain—all factors relevant to preeclampsia prevention." (PMID 40573136, 2025). "Insufficient levels of vitamin D can result in heightened inflammation and reduced insulin effectiveness, potentially raising the likelihood of developing preeclampsia and GDM." (PMID 41536823, 2025). "Increasing aOR with escalating glucose categories were seen for any complications, gestational hypertension, maternal insulin use, and primary Caesarean section." (PMID 39448754, 2024). "Gestational hypertension was significantly less frequent in the metformin-alone group and the metformin plus insulin group compared with insulin alone (6.2%, 23.3% and 36%, respectively)." (PMID 37798604, 2024). "Insufficient evidence is available on the short-term effect of lipid based nutritional supplements intervention on energy intake, appetite score and metabolic biomarkers like glucose and insulin levels in women with preeclampsia." (PMID 38206092, 2024). "The multifunctional nature of FLNB suggests potential interactions with established preeclampsia factors, including angiogenic/antiangiogenic proteins, insulin signaling defects, and immune dysregulation." (PMID 38099221, 2023). "In a study using the euglycemic clamp technique, compared with controls, women with gestational hypertension exhibited approximately 40% lower steady-state insulin sensitivity index and approximately 33% higher mean plasma TG." (PMID 36950677, 2023). "The three groups showed significant differences in fasting blood glucose and HbA1C, insulin treatment rate, and the incidence of pregnancy hypertension/preeclampsia and neonatal jaundice (all P < 0.05)." (PMID 36960096, 2022). "Maternal outcomes such as preeclampsia, CS and induction of labor were also significantly more common in the insulin-treated group compared to the diet group." (PMID 36014870, 2022). "GDM treated with insulin and preeclampsia treated with magnesium sulfate were more frequently observed in the older age group (0.9% vs. 2.6% vs. 5.4%, 0.2% vs. 0.5% vs. 0.9%, respectively; p < 0.0001)." (PMID 35207240, 2022). "It was concluded that MF, to a greater extent than insulin, reduces body weight gain in pregnant women, and also reduces the frequency and severity of gestational hypertension." (PMID 33429918, 2021). "An insulin-resistant preeclampsia model (performed at 40 weeks) that used angiotensin 2 type 1 receptor antibodies and a high-sugar diet at 40–48 weeks found that fasting insulin levels were also high." (PMID 33441894, 2021).
preeclampsia (continued). "Logistic regression analysis with enter selection confirmed that insulin therapy was closely correlated with development of gestational hypertension (GH)." (PMID 34579668, 2021). "Several selected biological processes and pathways were closely related to preeclampsia, including “cell junction assembly”, “neuron death”, “neurotrophin signaling pathway”, “insulin signaling pathway” and “AMPK signaling pathway”." (PMID 34696680, 2021). "A meta-analysis of oral antidiabetic drugs and insulin in GDM reported highest incidence of preeclampsia and hyperbilirubinemia with glyburide." (PMID 33403188, 2020). "A total of 14 (28%) of the patients treated with insulin and 12 (24%) of the patients treated with acarbose developed preeclampsia (p=0.64)." (PMID 33403188, 2020). "Metformin treatment of GDM reduces gestational weight gain (GWG), gestational hypertension, the incidence of neonatal hypoglycemia and the need for neonatal intensive care compared to insulin treatment." (PMID 32652973, 2020). "Three studies involving 564 GDM patients focused on the incidence of preeclampsia between glyburide and insulin." (PMID 31781670, 2019). "In the pairwise meta-analysis, we observed that metformin had lower incidence of preeclampsia than insulin (RR, 0.57; 95% CI, 0.45 to 0.72; P < 0.001)." (PMID 31781670, 2019). "In the pairwise meta-analysis, we observed that metformin had lower incidence of preeclampsia compared with insulin (RR, 0.56; 95% CI, 0.36 to 0.87; P < 0.01)." (PMID 31781670, 2019). "Variables were included in the model based on their associations in univariate analyses: mean fasting plasma glucose during the first trimester of pregnancy, gestational hypertension and insulin treatment." (PMID 30873116, 2019). "Preeclampsia was included as an outcome between metformin and insulin by 14 studies which involved 3402 GDM patients." (PMID 31781670, 2019). "The pooled result showed no significant statistical difference between the glyburide and insulin groups in terms of preeclampsia (RR, 0.98; 95% CI, 0.56 to 1.74; P = 0.95)." (PMID 31781670, 2019). "Although women in this study had mild preeclampsia, there was a significant relationship between microvascular blood flow, antiangiogenic factor ratio and insulin resistance." (PMID 28455450, 2017). "This study is the first to examine the relationship between microvascular blood flow, circulating markers of angiogenesis, insulin resistance, and endothelial activation together in preeclampsia." (PMID 28455450, 2017). "Their results proposed apprehension for the use of metformin because of the raised rate of preeclampsia (32% metformin versus 7% glyburide versus 10% insulin) and intrauterine fetal death (8% versus 0% versus 2.3%, correspondingly)." (PMID 27597988, 2016). "On the one hand, preeclampsia sera expectedly enhance inflammatory activities, including immune response, oxidative stress, insulin resistance, and adipogenesis, in adipose tissue." (PMID 26089598, 2015). "Their fasting blood glucose and insulin were also measured after diagnosis of preeclampsia by 20 weeks of pregnancy." (PMID 24812607, 2014). "Mean score for the level of fasting insulin among people with preeclampsia was higher than that of control group (P < 0.01)." (PMID 24812607, 2014). "Levels of fasting insulin and glucose were substituted into the formula and resistance to insulin was studied among the case and control groups both before and after the development of preeclampsia." (PMID 24812607, 2014). "Among the samples stimulated with insulin, the expression in the control group (n = 12) was 1.26 ± 0.16 and in the preeclampsia group (n = 12), it was 1.01 ± 0.11 (P = 0.23)." (PMID 22249794, 2011). "The expression of Akt/PKB in preeclampsia patients and controls, both at the baseline and in insulin-stimulated placenta samples, was similar." (PMID 22249794, 2011).
preeclampsia (continued). "If confirmed, our findings suggest research focusing on fetal insulin may help elucidate preeclampsia disease mechanisms." (PMID 41282652, 2025). "Whether intranasally administered insulin and hypoglycaemic agents improve executive function after preeclampsia requires further research." (PMID 40302139, 2025). "Blood–brain barrier integrity together with insulin resistance may be pivotal biological elements in the observed epidemiological relationship between executive function performance and a history of preeclampsia." (PMID 40302139, 2025). "In the following sections, we will discuss the role of insulin and leptin in preeclampsia as these factors are altered in the obese mouse model of preeclampsia—i.e., feeding ASB4-null mice with a high-fat diet (HFD), as described in the last section of this review." (PMID 39201703, 2024). "For example, analyzing and monitoring levels of leptin, adiponectin, FT4, insulin and CRP could assist in early identification of women at risk for preeclampsia or development of GDM." (PMID 36520252, 2023). "Future studies must, therefore, include whether neuronal glucose regulation also contributes to the exaggerated insulin increase in the maternal circulation during pregnancy and whether the genetic variants of ASB4 influence preeclampsia." (PMID 36768469, 2023). "Interrogation of maternal insulin in preeclampsia may reveal novel pathways to target for prevention." (PMID 36768469, 2023). "With regard to suggestive outcomes, metformin or any treatment were nominally significant in reducing the risk of preeclampsia when compared to insulin and no treatment respectively." (PMID 37072764, 2023). "Interestingly, we found three pathways potentially associated with preeclampsia: MAPK signalling pathway (FDR = 0.006), TGF-β signalling pathway (FDR = 0.011), Insulin signalling pathway (FDR = 0.020) and VEGF signalling pathway (FDR = 0.031)." (PMID 36292666, 2022). "Interestingly, although women with eDiP differed from those with eGDM with respect to insulin resistance and glucose metabolism, both subgroups had a similar proportion of women with chronic and gestational hypertension." (PMID 35407384, 2022). "Similarly, metformin treatment that leads to decreased insulin levels is thought to prevent the development of preeclampsia." (PMID 35258482, 2022). "Gestational hypertension and reduced liver insulin sensitivity were more common in this subset." (PMID 34815335, 2021). "Another mechanism for the prevention of preeclampsia may be a MF-induced decrease in IR and normalization of insulin levels in women with GDM, since there is an evidence that a decrease in insulin sensitivity is an important factor provoking preeclampsia." (PMID 33429918, 2021). "No clear trend regarding the effectiveness of continuous subcutaneous insulin infusion can be derived regarding pregnancy- and birth-related outcomes such as maternal weight gain, preterm births, cesarean delivery, maternal hypertension, or preeclampsia." (PMID 33908894, 2021). "Third, high leptin levels may promote preeclampsia through altering insulin levels, signalling transduction, reaction with other proteins and metabolism." (PMID 32807109, 2020). "The randomized investigations of diabetic pregnant women indicated a 47% risk reduction for gestational hypertension compared with insulin; however, there was no significant reduction for PE." (PMID 33381040, 2020). "Strikingly, women with previous early-onset of preeclampsia have significantly higher fasting blood glucose, insulin, triglycerides, and total cholesterol levels as compared to women with late-onset preeclampsia at the time of follow-up even 3 months postpartum." (PMID 32252821, 2020). "This may be explained by IRS-1 and IRS-2 inhibition due to serine-phosphorylation and subsequent impairment of downstream insulin signaling in preeclampsia." (PMID 27738431, 2016).
preeclampsia (continued). "Preeclampsia developed in 13 patients of the metformin group and in 12 patients of insulin group." (PMID 27597988, 2016). "In addition, quadratic curvilinear associations of 2 hG levels with pregnancy complications were observed in any complications, gestational hypertension, pre-eclampsia, preterm birth, maternal insulin use, primary Caesarean section, shoulder dystocia, LGA and NICU admission." (PMID 39448754, 2024). "Additionally, pathways such as the AMPK signaling pathway and insulin signaling pathway might provide meaningful clues for understanding the pathogenesis of preeclampsia." (PMID 34696680, 2021). "Thus, preeclampsia sera might contribute to insulin sensitivity by positive and negative regulation of the expression of diverse genes." (PMID 26089598, 2015). "Women who are diagnosed with pregnancy complications such as preeclampsia and GDM are generally more likely to be insulin resistant in the postpartum period compared to those with an uncomplicated pregnancy." (PMID 37468924, 2023). "Current research has found that the abundance of Clostridia_vadinB60_group positively correlated with the fasting insulin level and HOMA-IR, especially in overweight pregnant women or patients with preeclampsia." (PMID 38188576, 2023). "In a randomized, open-label study of pregnant women with PGDM, there were less gestational hypertension (p = 0.029) and maternal weight gain (p < 0.001) in the MET-treated group compared to the insulin-treated group." (PMID 33381040, 2020). "Lower educational level increased risks for many maternal complications, including preeclampsia, early onset preeclampsia, severe preeclampsia, GDM (on insulin), placenta previa and PPH." (PMID 30115949, 2018). "The mechanisms behind these opposite effects of insulin involve activation of A1 and A2A adenosine receptors leading to modulation of the biological effect of insulin in HUVECs from normal pregnancies, GDM pregnancies, and in preeclampsia." (PMID 25875935, 2015). "The aim here was to investigate insulin stimulation of the Akt/PKB pathway in the placenta, in normal and preeclampsia parturients." (PMID 22249794, 2011). "Compared to women without gestational hypertension, women with gestational hypertension had higher fasting insulin levels, but the difference had no statistical significance (P = .167)." (PMID 38739541, 2025). "Women with a history of preeclampsia, as compared with their BMI-matched counterparts without such a history, have higher circulating levels of fasting insulin and lipids, years after delivery." (PMID 25242982, 2012). "The aims of this study were to achieve in vitro insulin stimulation of the human placenta and to investigate the expression of the protein Akt/PKB in the baseline state and after stimulation, in the placentas of normal and preeclampsia patients." (PMID 22249794, 2011). "Sample stimulation was assessed by comparing the expression of phosphor-Akt (Ser473) in samples stimulated with insulin (+) and not stimulated (-), both in the control group and in the preeclampsia group." (PMID 22249794, 2011). "In addition, this study did not include variables between the group treated with oral hypoglycemic agents or insulin and without treatment and parameters related to adverse outcomes such as preeclampsia." (PMID 36078881, 2022). "Our finding that the need of insulin supplementation in pregnant women under GCs treatment receiving αMD for gestational hypertension is reduced by 30% compared to women not receiving αMD may raise the hypothesis that αMD may ameliorate glucose levels in pregnancy by increasing insulin sensitivity." (PMID 35052298, 2022).
lipid metabolism disorders (136 papers, 2014 to 2026). "It is caused by a deficiency in the production or function of insulin or both, which can occur because of different reasons, resulting in protein and lipid metabolic disorders." (PMID 32296622, 2020). "Previous studies have found that abnormalities in insulin signaling pathways caused by lipid metabolism disorders, inflammatory responses, oxidative stress, endoplasmic reticulum stress, and mitochondrial dysfunction lead to IR." (PMID 31258478, 2019). "GABA may also play a role in the treatment of lipid metabolism disorders caused by type 1 and 2 diabetes by inducing pancreatic β-cells and stimulating insulin secretion." (PMID 36560955, 2022). "However, the usage of β-blockers can cause glucose and lipid metabolism disorders and is due to the blockade of β2-AR-dependent insulin release from the pancreatic islets of Langerhans." (PMID 36213457, 2022). "Considering that AKT1-deficient adipocytes are less sensitive to insulin, menopause may thus interfere with lipid storage, leading to lipid metabolism disorders." (PMID 35707470, 2022). "The mechanism of lipid metabolism disorder in patients with PA may include abnormal insulin metabolism caused by elevated blood pressure, increased insulin levels, and increased gluconeogenesis by TG." (PMID 34194493, 2021). "Consequently, the insufficient secretion of insulin in the diabetic rats not only caused carbohydrate and lipid metabolism disorders but also led to protein metabolism disorders, including decreased protein synthesis and strengthened protein catabolism." (PMID 28100702, 2017). "Plasma INS concentrations in aged dogs were higher than those in young dogs, which may suggest an association between lipid metabolic disorder and insulin resistance with aging in dogs." (PMID 24597741, 2014). "Furthermore, Motor system disorders resulting from different diseases such as MS and RA, which led to decreased physical activity, long-term use of corticosteroids in RA, and insulin use in T1D patients, can cause lipid metabolism disorders and weight gain in patient." (PMID 37767101, 2023). "High concentrations of fatty acids impair insulin signaling pathways and decrease insulin sensitivity, which further exacerbates adipose tissue mobilization and again leads to lipid metabolic disorders, thereby triggering a vicious cycle." (PMID 40184169, 2025). "METS-IR, as a novel scoring system for screening insulin sensitivity, significantly improves the specificity of IR assessment by integrating body fat accumulation reflected by BMI, glucose-lipid metabolism disorders, and the inverse regulatory effect of HDL-C." (PMID 40700433, 2025). "The generally accepted mechanisms include lipid metabolism disorders, insulin resistance, systemic inflammatory response, and damage to internal organs and blood vessels caused by oxidative stress." (PMID 40406231, 2025). "AMSCs improve insulin secretion capacity and ameliorate glucose and lipid metabolism disorders through the repair of pancreatic injury in DCM mice." (PMID 40708699, 2025). "Studies have shown that T2DM is often accompanied by other glucose and lipid metabolic disorders, which manifest as decreased insulin secretion and disordered glucose homeostasis and lipid metabolism." (PMID 40855011, 2025). "Lipid metabolism disorders in the liver have been repeatedly demonstrated to result in decreased hepatic insulin sensitivity." (PMID 38613036, 2024). "Firstly, overexpression of TRIM21 improved hepatic insulin sensitivity and ameliorated systemic glucose and lipid metabolism disorders." (PMID 37249651, 2023). "Mogroside V can effectively regulate the insulin resistance of HepG2 cells and improve the blood glucose levels, insulin sensitivity, glucose and lipid metabolism disorders, and oxidative stress in T2DM rats." (PMID 37048193, 2023).